GLP1R (glucagon like peptide 1 receptor)
Diseases named in the same sentence as GLP1R in open-access papers (continued):
Sharing a sentence is not in itself a finding about the gene and the disease.
hepatocellular carcinoma (14 papers, 2019 to 2026). A malignant tumor that arises from hepatocytes. "In the literature, GLP1R‐agonists have had more variable effects on cellular senescence—liraglutide induced cellular senescence and had an anti‐proliferative effect in hepatocellular carcinoma cells, while exendin‐4 downregulated the expression of p16 and p21Cip1 in rat osteoblasts." (PMID 40448295, 2025).
Nephropathy (14 papers, 2014 to 2025). A nonspecific term referring to disease or damage of the kidneys. "GLP1R agonists numerically reduced the rates for nephropathy but the risk for retinopathy was similar." (PMID 30223891, 2018). "The rates for nephropathy was numerically lower in patients with GLP1R agonists than placebo (648/13680 versus 757/13709, OR: 0.80, 95% CI: 0.60 to 1.06, P = 0.121)." (PMID 30223891, 2018). "Therefore, we guess that the dysfunction of GLP-1R signaling pathway may be one of the reasons of kidney damage in obese mice induced by HFD." (PMID 34159197, 2021). "In addition, we found reduced expression of GLP-1R in the diabetic rats, which was restored in the sitagliptin-treated rats, suggesting a role of GLP-1R signaling in the amelioration of nephropathy, according to other reports." (PMID 24817793, 2014).
osteoarthritis (14 papers, 2018 to 2025). A noninflammatory degenerative joint disease occurring chiefly in older persons, characterized by degeneration of the articular cartilage, hypertrophy of bone at the margins and changes in the synovial membrane. "There is significant interest in the potential of glucagon-like peptide 1 receptor agonists (GLP-1A) to improve outcomes in osteoarthritis." (PMID 39995585, 2025). "We systematically reviewed the evidence from pre-clinical and human studies for effect of glucagon-like peptide 1 receptor agonists (GLP-1A) in osteoarthritis." (PMID 39995585, 2025). "GLP-1R signaling plays a key role in osteoarthritis (OA) by modulating inflammation, cartilage and bone metabolism, adipogenesis, and nociception." (PMID 41266905, 2025). "Importantly, GLP-1R is expressed in cartilage and its agonist liraglutide is shown to exert beneficial effects on joint tissue health in the context of osteoarthritis." (PMID 38510179, 2024). "The control group could be either the general population or those with osteoarthritis who were treated with the following: NSAIDs (non-steroidal anti-inflammatory drugs), opioids, paracetamol, GLP-1 RAs (Glucagon-like peptide-1 receptor agonists), hip or knee arthroplasty, or exercise." (PMID 40941581, 2025).
sarcopenia (14 papers, 2020 to 2026). Progressive decline in muscle mass due to aging which results in decreased functional capacity of muscles. "In contrast, treatment with the GLP‐1R agonist dulaglutide led to reductions in both markers of sarcopenia." (PMID 39764565, 2025). "Based on these data, DPP‐4/GLP‐1R‐targeting medications may hold promise as potential treatments for sarcopenia." (PMID 39764565, 2025). "However, we have detected elevated levels of GLP‐1 in starving individuals with sarcopenia and an increased level of GLP‐1R mRNA in the tibialis anterior muscle of sarcopenic mice (data not shown)." (PMID 38926763, 2024). "Weight loss due to treatment with metformin, sodium-glucose cotransporter 2 inhibitors, and glucagon-like peptide-1 receptor analogs can lead to sarcopenia in older patients without adequate exercise." (PMID 33139628, 2020). "Together, these diverse actions—spanning metabolic, inflammatory, oxidative, mitochondrial, and vascular domains—underscore the therapeutic potential of GLP-1RAs in counteracting sarcopenia in CKD, even in the absence of confirmed GLP-1R expression in human muscle cells." (PMID 40869417, 2025).
Hyperinsulinemia (13 papers, 2013 to 2026). An increased concentration of insulin in the blood. "The benefit of GLP-1R agonists for reducing chronic hyperinsulinemia might be one mechanism that explains the inhibitory effects on cancer risk in clinical studies and on cancer progression in preclinical settings." (PMID 41178720, 2025). "Another tumor-suppressive effect of GLP-1R agonists might be the ability to reduce basal hyperinsulinemia." (PMID 41178720, 2025).
colitis (12 papers, 2017 to 2025). Inflammation of the colon. "Glp1r–/– mice exhibited exacerbated intestinal inflammation in a dextran sulfate sodium–induced model of colitis." (PMID 41178710, 2025). "In DSS-induced colitis, when compared with GLP-1R+/+ mice, GLP-1R−/− mice displayed more severe intestinal injury." (PMID 37554552, 2023). "The GLP-1R KO mice exhibited much worse colon damage, significantly higher disease activity scores, and much more weight loss in response to DSS-induced colitis than wild-type controls." (PMID 36296337, 2022). "Upon dextrane sulfate (DS)-induced colitis, colonic Tff2, Tff3, Tgfb1, and Tgfb3 mRNA levels are significantly lower in Glp1r–/– mice compared to wild-type controls." (PMID 34660576, 2021). "Genes involved in innate immunity and inflammation, which are lower in Glp1r–/– at baseline, increases in both WT and Glp1r–/– in DSS-induced colitis, but differences between genotypes are lost." (PMID 34660576, 2021). "The complexity of GLP-1R signaling, inflammation, and microbiota crosstalk is further evidenced by the fact that in the gut, germ-free GLP-1R knockout mice exhibit increased mortality and develop colitis phenotypes, both of which can be rescued by transplantation of healthy microbiota." (PMID 40972535, 2025). "Furthermore, PC 1/3 and GLP-1R expression levels were increased in mice with colitis as compared to controls." (PMID 34535873, 2021). "In DSS-induced colitis, the severity of intestinal injury was increased in GLP-1R−/− mice." (PMID 29270177, 2017). "Therefore, GLP-1R can improve the symptoms of DSS-induced colitis in mice." (PMID 37554552, 2023). "Bone marrow transplantation, and therefore re-establishment of wild-type IELs in the intestinal mucosa, from wild-type donor mice to wild-type and Glp1r–/– recipient mice, normalizes colonic gene expression in response to DSS-induced colitis." (PMID 34660576, 2021). "Subsequent studies demonstrated that although GLP-1r mRNA levels was reduced in samples harvested from inflamed sites of IBD patients and colitis mice, GLP-1 levels were increased in sera of IBD patients when compared with healthy controls." (PMID 29270177, 2017). "Glp1r–/– mice lose significantly more weight, exhibit significantly increased disease activity scores and greater colon damage than wild-type controls in response to DSS-induced colitis." (PMID 34660576, 2021). "The effect of colitis on glucose level was studied by measurement of fasting glucose and GLP-1, dipeptidyl peptidase IV (DPP IV) levels, prohormone convertase 1/3 (PC 1/3) and GLP-1 receptor (GLP-1R) expression in mice." (PMID 34535873, 2021).
diabetic cardiomyopathy (12 papers, 2013 to 2025). Diabetic cardiomyopathy is a disorder of the heart muscle in people with diabetes. "The distinct novelty of our study is that it combines these complementary endpoints to delineate a coherent cytoprotective profile for a Lir in cardiomyocytes, thereby refining the mechanistic context for GLP-1R signalling in diabetic cardiomyopathy." (PMID 41155741, 2025). "One of the possible candidates for the treatment of diabetic cardiomyopathy is liraglutide, a glucagon-like peptide-1 receptor (GLP1R) agonist." (PMID 38543160, 2024). "Chronic administration of GLP1R agonists alleviated the development of diabetic cardiomyopathy in animals." (PMID 38732142, 2024). "We have previously demonstrated that GLP-1 and GLP-1R stimulation produced a peptide, which is critical to attenuate myocardial injury and to suppress the development of diabetic cardiomyopathy." (PMID 27875543, 2016). "In addition to attenuating myocardial oxidative stress and cardiac myocyte apoptosis, other potential mechanisms by which GLP-1R agonism may improve diastolic function and attenuate diabetic cardiomyopathy include an optimization of cardiac energetics." (PMID 33364978, 2020). "Recapitulating the observations reported in humans with T2DM, preclinical studies have also revealed that GLP-1R agonists induce robust cardioprotection (extensively reviewed in Ussher and Drucker, 2014; Drucker, 2016), actions that appear to extend to experimental diabetic cardiomyopathy." (PMID 33364978, 2020). "Glucagon-like peptide 1 receptor agonists (GLP-1RAs) and sodium-glucose cotransporter-2 inhibitors (SGLT2is) are antihyperglycemic agents with cardioprotective properties against diabetic cardiomyopathy (DCM)." (PMID 33503985, 2021). "Similarly, the glucagon-like peptide-1 receptor agonist liraglutide, an antidiabetic agent that promotes insulin secretion, also stimulates myocardial PDH activity and glucose oxidation, thereby alleviating the diastolic dysfunction in a murine model of diabetic cardiomyopathy." (PMID 36211560, 2022). "This suggests that GLP-1R agonism attenuates T2DM-related increases in myocardial oxidative stress and cardiac myocyte apoptosis, respectively, key mediators of diabetic cardiomyopathy, though diastolic function was not assessed in this particular study." (PMID 33364978, 2020).
glaucoma (12 papers, 2020 to 2026). Increased pressure in the eyeball due to obstruction of the outflow of aqueous humor. "By removing “glaucoma suspect” from the outcome definition, an even stronger protective association for incident glaucoma was found following GLP-1R agonist exposure (hazard ratio 0.08, 95% CI: 0.02 to 0.42, p = 0.003)." (PMID 37362000, 2023). "A recent association between exposure to GLP-1R agonists and a reduced risk of glaucoma makes it even more justified to consider the neuroprotective potential of GLP-1R agonists, particularly semaglutide, in anti-glaucomatous treatment strategies." (PMID 35264926, 2022). "Recently, a registry-based case-control study of 1,961 patients also associated the use of GLP-1R agonists with a reduced risk of glaucoma, strongly supporting further research into the use of agents that increase GLP-1R signaling as anti-glaucomatous treatment strategies." (PMID 35264926, 2022). "In addition, recent reports found a lower risk of POAG with glucagon‐like peptide‐1 receptor (GLP‐1R) agonists, while another study suggests that T2D patients treated with sodium‐glucose co‐transporter 2 (SGLT2) inhibitors have a reduced risk of incident glaucoma, compared to GLP‐1R agonists." (PMID 39449751, 2024). "This study, which included around 6,400 patients, employed Cox regression analysis and confirmed that diabetic patients using GLP-1R agonists—such as exenatide, liraglutide, dulaglutide, and semaglutide were less likely to receive a new glaucoma diagnosis." (PMID 40708853, 2025). "Another aspect of ophthalmology where GLP-1R agonist involvement is investigated is that of glaucoma." (PMID 41464694, 2025). "This work contributes to a growing body of evidence suggesting that GLP-1R agonists represent a viable therapeutic option for glaucoma." (PMID 37362000, 2023). "This study investigated neuroprotective effects of several commercially available GLP-1R agonists in a hypertensive mouse model of glaucoma." (PMID 37362000, 2023). "The present review aims to summarize current literature on antidiabetics in the treatment of neurodegenerative diseases with a special focus on GLP-1R agonists and glaucoma." (PMID 35264926, 2022). "The present review has summarized the current clinical evidence for a potential use of GLP-1R agonists in prospective neuroprotective treatment strategies against glaucoma and other neurodegenerative diseases." (PMID 35264926, 2022). "Emerging evidence suggests that glucagon-like peptide 1 receptor agonist (GLP-1RAs) may serve as promising neuroprotective agents in glaucoma." (PMID 40597179, 2025). "A growing body of evidence suggests that GLP-1R agonists may be protective in multiple neurodegenerative diseases including glaucoma." (PMID 37362000, 2023). "However, there are currently very few studies investigating the protective effects of GLP-1R agonists in the treatment of specifically glaucoma." (PMID 35264926, 2022). "Glucagon-Like Peptide 1 Receptor Agonists (GLP-1RAs), originally developed for diabetes, are currently being investigated for their neuroprotective potential in neurodegenerative conditions, including glaucoma." (PMID 40597179, 2025). "Moreover, certain observational studies have shown a reduction in the development of primary open-angle glaucoma (POAG) and ocular hypertension (OHT) in patients using GLP-1R agonists compared to other diabetic oral medications." (PMID 41464694, 2025). "Previously, the glucagon-like peptide-1 receptor (GLP-1R) agonist NLY01 was shown to reduce microglia/macrophage activation, rescuing retinal ganglion cells after IOP elevation in an animal model of glaucoma." (PMID 37362000, 2023). "1,961 patients with no baseline glaucoma, glaucoma suspect nor ocular hypertension who newly initiated GLP-1R agonist treatment, e.g., semaglutide, were compared to an unexposed control group." (PMID 35264926, 2022).
glaucoma (continued). "Treatment with the GLP-1R agonist NLY01 reduced microglia/macrophage production of IL-1α, TNF-α, and C1q; decreased A1 astrocyte conversion; and protected against RGC death in this mouse model of glaucoma." (PMID 33147455, 2020). "Results further support a role for GLP-1R agonists as a commercially available class of agents with a known safety profile that may provide a supplemental approach to treating glaucoma without relying exclusively on IOP lowering." (PMID 37362000, 2023).
Cirrhosis (11 papers, 2019 to 2026). A chronic disorder of the liver in which liver tissue becomes scarred and is partially replaced by regenerative nodules and fibrotic tissue resulting in loss of liver function. "For treating T2DM, glucagon-like peptide-1 receptor agonists and coagonists, sodium-glucose cotransporter-2 inhibitors, metformin (if glomerular filtration rate exceeds 30 mL/min), and insulin (in decompensated cirrhosis) are preferred." (PMID 41752724, 2026).
cognitive decline (11 papers, 2021 to 2026). "Taken together, reduced GLP-1R in the basal ganglia of the aged brain is associated with cognitive decline in AD through dysfunctional clearance of amyloid." (PMID 38915346, 2024). "Clinical studies further indicate that GLP-1R agonists alter neural responses to reward-related cues, influence mood-related outcomes, and are associated with reduced risk of cognitive decline, although results pertaining to benefits in neurodegenerative disease remain mixed." (PMID 41876956, 2026). "The aim of this study was to test the hypothesis that aging with sustained glucose intake, which reduces availability of cerebral GLP-1R, contributes to cognitive decline of the brain, leading to CH and/or AD depending on functionality of metabolic clearance." (PMID 38915346, 2024). "GLP-1R activation ameliorated cognitive decline through a pathway independent of glucose metabolism." (PMID 41480353, 2025).
myocardial ischemia (11 papers, 2011 to 2025). A disorder of cardiac function caused by insufficient blood flow to the muscle tissue of the heart. "Our data indicate that postsynaptic GABABRs in cardiomyocytes interact with GLP-1R to modulate spontaneous membrane potential, implicating a potential antiarrhythmic role following cardiac ischemia." (PMID 41244817, 2025). "Recently, GLP-1 has been shown to reduce an infarct size in both in vitro and in vivo animal models of cardiac ischemia/reperfusion injury and exendin-4 (Ex-4), an exogenous GLP-1R agonist isolated form the Gila monster lizard, has reported to have very similar effects." (PMID 25194961, 2014). "In addition, GLP-1R expression in the cardiovascular system confers direct cardioprotection on GLP-1, manifesting as reduced myocardial ischemia–reperfusion injury and improved cardiac function, thereby further broadening the physiological regulatory value of GLP-1R." (PMID 41573745, 2025). "After linagliptin treatment, the WB density of GLP-1R was significantly increased in both the CKD and CKD with myocardial ischemia groups." (PMID 30823876, 2019). "WB revealed significant decreases in renal tubular GLP-1R expression 8 weeks after CKD and CKD with myocardial ischemia." (PMID 30823876, 2019). "GLP-1R protein levels were significantly increased in both CKD and CKD with myocardial ischemia groups after linagliptin treatment." (PMID 30823876, 2019). "In contrast, GLP-1 receptor (GLP-1R) activation has been shown to confer both renal and cardiovascular protection, though its relationship with CKD and CKD with myocardial ischemia/reperfusion (MI/R) remains poorly understood." (PMID 30823876, 2019). "WB of myocardial GLP-1R was significantly increased 8 weeks after CKD onset, with the strongest changes seen in CKD with myocardial ischemia." (PMID 30823876, 2019). "In recent years, the glucagon-like peptide-1 receptor agonist (GLP-1RA), a new type of hypoglycemic drug, has been shown to regulate blood sugar levels, improve myocardial ischemia, regulate lipid metabolism, improve endothelial function, and exert a protective role in the cardiovascular system." (PMID 35434139, 2022). "IHC analysis of myocardial tissues showed increased GLP-1R in the ischemic area after LAD ligation, relative to control, though differences between days 1, 3, and 7 post-myocardial ischemia were not statistically significant." (PMID 30823876, 2019).
Cerebral ischemia (10 papers, 2016 to 2025). Restriction of arterial blood supply to the brain associated with insufficient oxygenation to support the metabolic requirements of the tissue. "Our previous studies have also shown that multiple GLP-1R agonists can play neuroprotective role in diabetic rats with cerebral ischemia–reperfusion injury, PD mice, status epilepticus rats and other disease models without relying on blood glucose." (PMID 40606832, 2025). "The glucagon-like peptide-1 receptor (GLP-1R) agonist Exendin4 (EX-4) binds to astrocyte surface GLP-1R to protect the BBB and reduce secondary inflammation caused by cerebral ischemia." (PMID 35321205, 2022). "The glucagon-like peptide-1 receptor (GLP-1R) agonist exendin-4 (Ex-4) protects the BBB and reduces brain inflammation from cerebral ischemia, and GLP-1R is expressed on astrocytes." (PMID 31779652, 2019). "While the glucagon-like peptide-1 receptor (GLP-1R) agonist exendin-4 (Ex-4) is known to protect against oxidative stress and neuronal cell death caused by ischemic brain damage, its effect on preventing warfarin-associated HT after cerebral ischemia is yet unknown." (PMID 27566245, 2016).